IL2 (interleukin 2)
Diseases named in the same sentence as IL2 in open-access papers (continued):
Sharing a sentence is not in itself a finding about the gene and the disease.
tumor (continued). "Adoptive cell therapy (ACT) is an immunotherapy where T cells, for example, tumor-infiltrating lymphocytes (TILs), are grown out from a patient’s tumor or blood, expanded in vitro in the presence of human IL-2, and later infused back into the same patient." (PMID 39131259, 2022). "They investigated the therapeutic potential of Alb-IL2 and demonstrated improved survival outcomes, reduced tumor growth, and significant infiltration of T cells in tumors when compared to IL-2." (PMID 35962391, 2022). "Subsequent longitudinal 2D BLI imaging demonstrated an accumulation of EGFR CAR T cells ± IL-2 at the tumor site in the following two weeks, while control-treated animals exhibited a signal in an area attributable to the spleen in dorsal and ventral view." (PMID 35836798, 2022). "Rosenberg and his colleagues found that the addition of IL-2 to cultured lymphocytes promoted lymphocytes to lyse autologous tumor cells." (PMID 36077696, 2022). "Both CD4+ Tconv cells and Tregs from the tumor expressed less IL-2 than corresponding circulating T cells in the PR cohort." (PMID 36509285, 2022). "As observed in the previous results, the ratio of Pmel-1 increased in the lymphoid and tumor tissues when the animals were treated with the TBI/IL-2 combination." (PMID 36497152, 2022). "CAR-T cells that were exposed to IL-2 and IL-15 secreted more proinflammatory cytokines and presented stronger tumor-lysis ability in vitro." (PMID 36172343, 2022). "Due to the inhibiting effect of IL-2, IL-24 and IL-27 on EC cells, there are bright prospects for them to be used as anti-tumor drugs." (PMID 36531027, 2022). "The erlotinib treatment (TB-E group) also resulted in lower PD-L1 and IL-2 mRNA levels than in untreated tumor-bearing mice." (PMID 36547898, 2022). "Infusing tumor-infiltrating lymphocytes (TIL) along with interleukins like IL-2 and lympho-conditioning showed promising results in a subset of patients with metastatic melanoma." (PMID 36253762, 2022). "We investigated TBI/IL-2-induced changes in these subsets by conducting multiparametric flow cytometry analysis of the cells isolated from spleen and tumor tissue." (PMID 36497152, 2022). "COR inhibited tumor growth and elongated survival time of tumor-bearing mice by regulating the expression of cytokines such as IL-2, IL-4, TNF-α, TGF-β and IFN-γ." (PMID 35200422, 2022). "Meanwhile, FO/Se treatment resulted in higher levels of plasma IFN-γ and IL-2 together with lower IL-6 in doxorubicin-treated tumor-bearing mice than does doxorubicin treatment alone." (PMID 36483592, 2022). "For the first time, the correlation of the salivary levels of TNF-α, IL-1β, and IL-6 with HER2 status, MCP-1, IL-1β, IL-2, and IL-4 with the hormonal status of the tumor was shown." (PMID 36286034, 2022). "In H22 tumor-bearing mice, STRGD inhibited tumor growth, enhanced interleukin-2 and natural killer cell activity, and restored and improved suppressed immune function." (PMID 35754689, 2022). "The co-administration of DNA encoding IL-2 in tumour-bearing mice elicited a stronger CTL response and enhanced anti-tumour effects." (PMID 35805007, 2022). "Consistent with earlier observations, large-format IL-2 delayed tumor outgrowth more than small-format IL-2." (PMID 35013154, 2022). "In vitro treatment of NK cells with Hsp70 and IL-2 promotes cellular activation and greater antitumor cytotoxic activity, leading to the selective death of tumor Hsp70+ cells." (PMID 35203609, 2022). "The resulting bypass channel for IL-2 production allows for improved tumor control and reduced toxicity compared to alternative mechanisms of IL-2 delivery." (PMID 36520915, 2022). "IL-2 therapy prevented tumor progression, presumably due to the early expansion of effector T cells promoted by IL-2." (PMID 35983059, 2022).
tumor (continued). "Thereafter, antigen-activated and -nonactivated CAR T cells displayed distinct accumulation kinetics: while in the EGFR CAR T cell (± IL-2)-treated cohorts, the first signal emerged at the tumor site, BDCA-2 CAR T cells (± IL-2) primarily homed to the spleen." (PMID 35836798, 2022). "Several recent studies have revealed the superiority of IL-7/IL-15 over IL-2 in ex vivo expanding human naïve or tumor-experienced CD8+ T cells as well as CAR-T cells." (PMID 36394017, 2022). "Whilst combining DMXAA with IL-2 or anti-CD40 antibody reduced tumor size, long-term survival was compromised as mice that were apparently cured of their tumors died." (PMID 36466911, 2022). "Within its numerous functions, IL-2 is capable of recruiting cytotoxic T-lymphocytes selectively to tumours." (PMID 35324835, 2022). "Exposure of TKD/IL-2 stimulated NK cells and anti-Hsp70 CAR T cells to CRC cells expressing mHsp70 triggers GrB-mediated cytotoxicity and IFN-γ release which causes tumor control in vitro." (PMID 35720311, 2022). "Of interest, in an immune-tolerant state after transplant, exogenous IL-2 triggered effector T-cells to exert an anti-tumor effect with maintaining GVHD suppression." (PMID 35983059, 2022). "HPBMC were activated and expanded with anti-CD3/CD28 antibodies and IL-2, before co-culturing with tumor cells." (PMID 35154166, 2022). "In vitro, IL-2-activated NK cells can facilitate the presentation of tumor antigens by dendritic cells via MHC-I, improving the activation of Ag-specific CD8+ T lymphocytes." (PMID 35203609, 2022). "In vivo experiments showed that FAVO significantly delayed the growth of SGC-7901 tumor-bearing nude mice and induced higher serum IL-2 and IFN-γ and reduced serum IL-6." (PMID 35392643, 2022). "TGF-B1 is a potent inhibitor of T cell growth, partly by inhibiting IL-2 expression and secretion by T cells themselves, and interestingly, it can also affect anti-tumor T cell responses by downregulating MHC molecules on the surface of tumor cells." (PMID 35311155, 2022). "Like many immunotherapies, IL-2 elicits exposure-dependent anti-tumor effects, making it a model immunomodulator to test the impact of pharmacokinetic properties on therapeutic efficacy." (PMID 35013154, 2022). "After injection, held-up IL-2 fusion protein toggles between four states within the tumor: unbound, bound to collagen, bound to IL-2 receptor (IL-2R), or concurrently bound to both targets." (PMID 35013154, 2022). "Here instead we use a different strategy: harnessing the power of an engineered cell to identify a tumor and locally deliver IL-2 exactly where it is needed." (PMID 36520915, 2022). "This was achieved via either transabdominal ultrasound-guided intralesional injection of IL-2, endoscopically/transrectally assisted or by IL-2 injection into the tumour bed after cytoreductive (palliative) surgical tumour resection." (PMID 35324835, 2022). "Both isogenic tumor cell systems were used as targets to demonstrate the mHsp70 specificity of TKD/IL-2 activated NK cells and anti-Hsp70 CAR T cells." (PMID 35720311, 2022). "Compared with traditional CAR-T cells, IL-7 and CCR2b co-expressing CAR-T cells boosted self-survival and migration, enhanced IFN-γ, Gzms-B, and IL-2 expression, and obstructed tumor growth." (PMID 36168626, 2022). "Supporting this, it was observed that tumour-specific T cells in combination with IL-2 obtained complete neoplasm eradication." (PMID 35406451, 2022). "Most current efforts in IL-2 engineering have focused on engineering the cytokine to be more selective for a tumor." (PMID 36520915, 2022). "The first was inflammation-related pathways, such as the IL6/JAK/STAT3 signalling, inflammatory response, IL2/STAT5 signalling, TNF-alpha signalling via NFKB, and KRAS signalling pathways, which have been proven to be associated with tumours." (PMID 35246158, 2022).
tumor (continued). "The transduced T cell lines were then tested for activation as measured by IL-2 secretion upon challenge by a panel of tumor cell lines pre-treated with IFN-γ to upregulate class I MHC expression." (PMID 35812387, 2022). "Several other targets have been assessed for their ability to deliver IL-2 to the tumor site; these include carcinoembryonic antigen (CEA) and fibroblast activation protein (FAP)." (PMID 35104810, 2022). "By placing IL-2 production under the control of a new TCR-independent but still tumor-targeted synthetic receptor we can now produce IL-2 immediately and consistently after tumor entry despite suppression of T cell activation." (PMID 36520915, 2022). "IL-2 is capable of eliciting durable tumor regression via natural killer (NK) and T cell activation but is plagued by severe systemic toxicity." (PMID 35013154, 2022). "IL-2, IL-9 and IL-15 show tumor-suppressive effects in CRC, while IL-4 and IL-7 exert pro-tumorigenic effects." (PMID 36611932, 2022). "Our data indicate that both blockade of inhibitory KIR and IL-2 triggering of tumor-derived NK-cells are necessary to enhance NK-cell responsiveness in GBM." (PMID 35474089, 2022). "This significant antitumor effect translated into improved survival of tumor-bearing mice, with 75% of mice treated with Salmonella and Alb-IL2 surviving past 100 days." (PMID 35962391, 2022). "As a single agent, IL-2 therapy cannot overcome immune resistance barriers posed by the tumor microenvironment." (PMID 35013154, 2022). "The contribution of lymphocytes from peripheral blood, and their early increase, to the tumor response in mRCC patients treated with immunotherapy was already demonstrated with interleukin-2 treatment." (PMID 36212433, 2022). "A higher level of IL-2 is associated with damage to regional lymph nodes and low tumor differentiation, as well as HER2-positive and ER-negative tumor status and a high level of Ki-67 expression." (PMID 36286034, 2022). "Our results clearly demonstrated the ability of Salmonella + Alb-IL2 to control tumor growth and provide durable immunity." (PMID 35962391, 2022). "An in vitro study showed that the inhibition of CTLA-4 receptors by ipilimumab has an impact on the release of IL-2 by tumor cells simultaneously regulating the tumor microenvironment and increasing the immune response." (PMID 36010854, 2022). "Previous studies have reported that Alb-IL2 demonstrated modest anti-tumor effects driven by T cell expansion and effector function." (PMID 35962391, 2022). "In one study, researchers constructed a trispecific immunocytokine (anti-NDV/IL2/anti-CD28) for efficiently targeting tumor cells." (PMID 36311790, 2022). "We find that an effective therapeutic response is only observed with an autocrine IL-2 circuit (i.e. synthetic IL-2 induction pathway is contained within the same cell as the anti-tumor CAR/TCR)." (PMID 36520915, 2022). "The selective targeting of oncogenic signaling molecules and the tumor immune microenvironment molecules (i.e., PD1/PD-L1/cytotoxic T lymphocyte associated antigen-4, CTLA-4/NKp-46/CD16/CD28/CD80/IL-2/IL-6) were evaluated." (PMID 36547898, 2022). "To design a tumor-induced synthetic IL-2 circuit in T cells, we used a synNotch sensor to induce the transcription of an IL-2 transgene." (PMID 36520915, 2022). "Existing literature has showed that IL-2 biased agonists preferentially expand CD8 T cells and NK cells over Tregs and contribute to improved anti-tumor responses compared to IL-2." (PMID 35962391, 2022). "The humanized immunocytokine hu14.18-IL2 was designed to selectively target malignancies and concentrate human IL2 at the tumor site by fusing human IL2 to the heavy chains of the intact humanized form of an anti-GD2 monoclonal antibody." (PMID 35799600, 2022).
tumor (continued). "In line with this, the dependence on T cell immunity was evidenced by the loss of tumor controlling abilities when CD4 and CD8 T cells were depleted prior to administration of Salmonella + Alb-IL2." (PMID 35962391, 2022). "An in-depth analysis of the tumor composition displayed a compliant expression pattern between EGFR and the epithelial marker CD326, whose levels decreased upon EGFR CAR T cell+IL-2 treatment indicating the highest tumor cell death in this cohort." (PMID 35836798, 2022). "One of the effective medical methods is immunocytokine therapy which can be achieved by transfecting cytokines such as IL-2 directly in tumor and adjacent tissues." (PMID 35466321, 2022). "Targeted delivery of IL2 to the tumor stroma can enhance the effects of immune checkpoint inhibitors by preferentially activating NK and CD8+ T cells." (PMID 35996406, 2022). "Targeted delivery of IL-2 is a novel approach to enhance the cytotoxicity effects of tumor resident NK cells." (PMID 36686835, 2022). "PEGylated IL-2 molecules that preferentially bind to different IL-2R conformations are being explored in oncology to controllably activate the IL-2 system and shift the balance in the tumor microenvironment in favor of effector T cells (Teffs)." (PMID 36405706, 2022). "Driven by memory B cells and a range of cytokines (including TNF, IL-2, IL-6, and IFNγ), T cells home to the tumor bed and release perforin and granzyme or Fas/FasL pathways to destroy tumor cells." (PMID 36704336, 2022). "IL-2 CAR T cells were robust in killing tumor cells both in vitro and in vivo, but overtime CAR T cells expanded in IL-7/15 outperformed IL-2 CAR T cells with increased expansion and improved persistence." (PMID 35493513, 2022). "IMT/PTX resulted in significantly more necrotic tumor tissue and increased levels of IL-2, 4, and 12 compared to control." (PMID 35214172, 2022). "Oral melatonin at 40 mg daily amplifies the anti-tumor activity of IL-2 treatments in patients with solid neoplasms when given 7 days before IL-2 is administered." (PMID 35413810, 2022). "Th1 cells produce tumor necrosis factor alpha (TNF-α), interferon gamma (IFN-γ), interleukin (IL)-2 and IL-12 to mediate antitumor effects, while Th2 cells produce IL-4 and IL-10 which favor tumor growth." (PMID 35805995, 2022). "Local administration of IL-2 induces vascular leakage and tumour necrosis, with subsequent stimulation of an immune response." (PMID 35324835, 2022). "Variants of IL-2 such as NKTR-214 have been developed that only promote a minor expansion of Tregs, while enhancing anti-tumor responses." (PMID 35203256, 2022). "Solving the ODEs yields the total extracellular concentration of the injected IL-2 fusion protein, target-bound and freely diffusing, in the tumor over time." (PMID 35013154, 2022). "Exosomes from human tumor cells (mesothelioma cell line) was also found to selectively impair peripheral blood lymphocytes response to IL-2." (PMID 35031075, 2022). "In the absence of adoptive transfer of Pmel-1 T cells, TriVax combined with IL-2/JES6-5H4 also led to delayed tumor growth, but to a lesser extent." (PMID 35651800, 2022). "CD39+CD103+ tumor-resident memory T cells sorted from human high-grade EC differentially expressed IL-2, IL-10, IL-13, IL-17A, IL-21, and IL-22 before and after activation." (PMID 36531027, 2022). "Research has shown that cytokines such as INF-γ, TNFα, and IL-2 can enhance the anti-tumor function of CAR-T cells." (PMID 35935930, 2022). "In order to obtain sufficient exposure at tumor sites and induce tumor suppression with decreasing side effects, several investigations have focused on nanocarrier-based IL-2 application." (PMID 36014696, 2022). "Adoptive cell therapy consists of the isolation of TILs from the excised tumor, expansion of these cells by interleukin-2 (IL-2) treatment, and reinfusion into lympho-depleted patients with IL-2 treatment." (PMID 36125617, 2022).
tumor (continued). "To this aim, we isolated TILs from MC38‐derived tumor masses grown in control or Drp1‐cKO mice (treated with anti‐IgG or anti‐PD‐1) and let them expand in vitro in the presence of IL‐2, IL‐7 and IL‐15 cytokines." (PMID 34535949, 2022). "Preclinical studies showed that adoptive transfer of LAK cells into tumor-bearing mice resulted in anti-tumor activity, and the concomitant administration of IL-2 with LAK cells increased in vivo anti-tumor activity of LAK cells." (PMID 35720306, 2022). "CD4+ T cells can enhance the function of tumor specific CD8+ T cells by secreting interleukin-2, which can effectively promote tumor regression." (PMID 35577774, 2022). "This renewed interest in IL2 therapeutic potential occurs during a new era with more precise readouts for pharmacodynamic responses in the peripheral and tumor compartments." (PMID 36923304, 2022). "The cytotoxicity assessment by Annexin/PI staining method confirms the fast and efficient response of TKD/IL-2 activated NK cells against mHsp70-positive tumor cells." (PMID 35720311, 2022). "Early tumor immunotherapy mainly used cytokines produced by the immune cells to directly attack the tumor cells, such as IL-2 and IFN." (PMID 35664731, 2022). "Nevertheless, it seems that a more significant anti-tumour effect was achieved by the use of pro-inflammatory cytokines in combination with anti-PD1/PDL1 antibodies, such as demonstrated for IL-12 and IL-2 with TNFα encoding virus vectors." (PMID 36140243, 2022). "IL-2 was the first cytokine discovered to promote the growth of T cells, and recombinant IL-2 has shown anti-tumor activity in several mouse tumor models." (PMID 35296094, 2022). "Treatment with PD‐L1 siRNA and IL‐2 pDNA‐loaded TT‐LDCP NPs significantly suppressed the tumor growth and metastasis compared to that treated with TT‐LDCP loaded with control siRNA and HCC vaccine." (PMID 35343112, 2022). "Sharma and colleagues investigated the efficacy of bempegaldesleukin combination with ICI in animal tumor model and noticed the synergizing effects and the benefit of using this IL‐2 prodrug for potentiating the fraction of CD8+ T cells and cancer regression." (PMID 35301813, 2022). "IL-2 was the first cytokine employed in tumor treatment and the first reproducible and effective human tumor immunotherapy approved by the Food and Drug Administration (FDA)." (PMID 36560427, 2022). "T cells recognize tumor antigens, activate and amplify effector T cells, and secrete cytokines such as IL-2, IL-4, IL-5, IFN-γ and granase to exert cytotoxic killing effects." (PMID 35729189, 2022). "Previous studies have shown that the combination of radiotherapy or PD-L1 blockade and IL-2 therapy potently stimulates systemic anti-tumor immunity." (PMID 36569954, 2022). "IL-15 also induced increased killing in ZOL or BrHPP-activated Vδ2 T cells against different tumor cell lines (Daudi and U299 cells) compared to IL-2 alone." (PMID 36429001, 2022). "We delivered IL-2 as a fusion protein, Alb-IL2, which we demonstrate to have preferential accumulation properties, bringing it to the tumor and secondary lymphoid organs." (PMID 35962391, 2022). "We administered Salmonella + Alb-IL2 to both T-cell-depleted mice and normal tumor-bearing mice and observed a dramatic reduction in tumor control in T-cell-depleted mice, whereas control mice demonstrated robust anticancer effects." (PMID 35962391, 2022). "Blocking mTOR activity by rapamycin can promote memory cell precursors, especially the newly differentiated memory CD8+T cells equipped with more superior anti-tumor activity than IL-2-inducing effector T cells." (PMID 36200045, 2022). "This is especially interesting in the context of both therapeutic HIV vaccination and tumor immunology, where a reduction in IL-2 production is one of the first manifestations of exhaustion in CD8+ T cells." (PMID 35890284, 2022).